ALK (ALK receptor tyrosine kinase)
Diseases named in the same sentence as ALK in open-access papers (continued):
Sharing a sentence is not in itself a finding about the gene and the disease.
adenocarcinoma (continued). "In some NSCLC patients, mainly adenocarcinoma, molecular alterations in driver genes, like EGFR, KRAS, HER2, ALK, MET, BRAF, RET,ROS1, and NTRK are recognized." (PMID 37346803, 2023). "The rearranged anaplastic lymphoma kinase (ALK) oncogene is another example of genomic alterations in NSCLC and adenocarcinoma." (PMID 36290461, 2022). "We report a rare case of stage IV pulmonary combined large-cell neuroendocrine carcinoma (LCNEC) and adenocarcinoma (ACA), both demonstrating anaplastic lymphoma kinase (ALK) rearrangement by IHC and FISH." (PMID 35200571, 2022). "This study aimed to investigate the frequency, association with clinicopathological characteristics, and prognosis of the immunohistochemical expressions of ALK, NUT, and TRK in 477 adenocarcinomas of the stomach and gastroesophageal junction." (PMID 35204520, 2022). "When we analyzed individual genes, both ALK and ROS1 fusion patients still had a higher PD-L1 positive rates than wild type adenocarcinoma patients." (PMID 35980949, 2022). "Many oncogenic drivers of adenocarcinoma have been found in the clinic, such as the epidermal growth factor receptor (EGFR) and anaplastic lymphoma kinase (ALK)." (PMID 34845836, 2022). "Given the increasing number of treatment options, EGFR, ALK, ROS1 and BRAF testing is now required at the diagnosis of advanced adenocarcinoma to define the best first line treatment." (PMID 34884672, 2021). "Of the 12 cases of adenocarcinoma, 11 (91.7%) had adequate samples for all molecular tests including EGFR, ALK, and PD-L1." (PMID 34441366, 2021). "Bronchoscopic biopsy and IHC analysis revealed a poorly differentiated adenocarcinoma with positive expression of Napsin A, TTF‐1, CK7 and ALK (Ventana)." (PMID 34541785, 2021). "Regarding targetable molecular alterations, adenocarcinomas with STAS have been related to wild type epidermal growth factor receptor (EGFR), ALK rearrangement and Kirsten rat sarcoma viral oncogene homolog (KRAS) mutation." (PMID 32564261, 2020). "While the majority of tumors in all three molecular subgroups had adenocarcinoma histology, there was a higher frequency of neuroendocrine histology among RET+ tumors included in this study (RET: 12% vs ALK: 2%, p = 0.025; vs ROS1: 0%, p = 0.010)." (PMID 32183422, 2020). "ALK rearrangement is one of the crucial molecular alterations in NSCLC, especially in adenocarcinoma with the incidence between 2 and 13%." (PMID 32727606, 2020). "In summary, despite shared clinical and imaging features, ROS1-, ALK-, and EGFR-positive advanced adenocarcinomas differ in certain imaging features of the primary tumor and disease spread patterns." (PMID 33005033, 2020). "For instance, adenocarcinoma is generally induced in part to alterations in KRAS, ALK, ROS proto-oncogene 1 (ROS1), Ret proto-oncogene (RET), neurotrophic receptor kinase 1 and neuregulin." (PMID 32316322, 2020). "ALK testing is recommended in advanced NSCLC patients, particularly those with adenocarcinoma histology." (PMID 33273548, 2020). "The responses show that all countries follow guidelines regarding EGFR and ALK testing, with most countries testing only advanced stages of adenocarcinomas, NSCLC-NOS, and NSCLC when an adenocarcinoma component cannot be excluded." (PMID 29523116, 2018). "ALK rearrangements are found in approximately 2–7% of patients with NSCLC, almost all of which are adenocarcinomas." (PMID 29914100, 2018). "The efficacy of first line pemetrexed-based chemotherapy was investigated in patients with HER2-mutant and those with EGFR-mutant, ALK/ROS1-rearranged and KRAS-mutant advanced adenocarcinomas." (PMID 29587667, 2018). "Our cohort demographics were similar to previous reports in terms of smoking status, adenocarcinoma and median age, reflecting the expected characteristics of patients with NSCLC harbouring ALK gene rearrangement." (PMID 28209203, 2017).
adenocarcinoma (continued). "ALK rearrangement is the one of most frequent molecular alterations in NSCLC, particularly adenocarcinoma." (PMID 27142166, 2016). "FISH positive cases were all defined as adenocarcinoma (ADC) histologic subtype and the FNA samples showed the highest ALK positive rate (13.2%, 12/91)." (PMID 26789109, 2016). "Clinicopathological characteristics of a 54 year old female patient who had ALK rearrangements and EGFR wild type was smoker, adenocarcinoma histology and presence of metastasis." (PMID 27217997, 2016). "The frequency of the ALK rearrangement is approximately 6.7% in NSCLC in Japanese and 5% of NSCLC (adenocarcinoma, 96%) in USA." (PMID 24667320, 2014). "Initial reports have shown that ALK positive NSCLC patients tend to be younger, predominantly non/light smokers with an adenocarcinoma histology than the overall NSCLC patients population." (PMID 23359795, 2013). "Combined with data on the expected frequency of adenocarcinomas in the United States, screening 39% of the population with advanced stage NSCLC should, therefore, capture 89% of ALK rearrangements." (PMID 22374459, 2012). "This differs from recent guidelines in Switzerland and France (French National Cancer Institute; INCa) proposing ALK testing only by FISH and only in EGFR-negative KRAS-negative adenocarcinoma patients." (PMID 22825000, 2012). "A bronchoscopy with rebiopsy was practiced on 08/16/2023 and histopathological report and IHC tests from 08/2023 reconfirmed poorly differentiated adenocarcinoma, ALK-negative EGFR-negative and PD-L1 low expression (TPS = 5%)." (PMID 40429388, 2025). "A 39-year-old woman was diagnosed with Stage IV adenocarcinoma of the left lung, which tested negative for EGFR, ALK, and ROS-1 mutations, while showing a 2% expression of PD-L1 and an ERBB2 mutation." (PMID 41180730, 2025). "In patients diagnosed with adenocarcinoma or unspecified NSCLC without activating mutations in the EGFR gene, the status of the ALK and ROS1 genes should be evaluated to detect rearrangements that occur in 3–5% and 1% of patients, respectively." (PMID 40076671, 2025). "Research shows that ALK tyrosine kinase rearrangements exist in 4 percent of U.S. NSCLC adenocarcinomas, while they occur most frequently in non-smokers and younger individuals." (PMID 40332427, 2025). "A 39-year-old woman diagnosed with Stage IV adenocarcinoma of the left lung, negative for EGFR, ALK, and ROS-1, but with an ERBB2 mutation, experienced neurological symptoms leading to a diagnosis of brain metastasis in 2019." (PMID 41180730, 2025). "As for EGFR mutations and ALK fusions, ROS1 is more common for non-smokers and patients with an adenocarcinoma histology." (PMID 40136350, 2025). "Patients who lack EGFR, ALK ROS1, and KRAS driver mutations tend to have these fusions along with younger age groups, non-smokers, and those with adenocarcinoma pathologies." (PMID 40332427, 2025). "Chromosomal rearrangements involving ALK have been identified as an oncogenic driver in 3–7% of patients with NSCLC and have been associated with non-smoking status, younger age, and adenocarcinoma histology." (PMID 40234387, 2025). "The EGFR- and ALK-targeted cohorts were younger with the highest proportion of adenocarcinoma and never-smokers." (PMID 41139898, 2025). "The histopathological examination revealed a poorly differentiated adenocarcinoma, ALK, EGFR, PDL 1 negative, cT3 N3 M1b (OSS, single, right humeral head) and stage IVA." (PMID 40429388, 2025). "ALK fusion–positive is predominantly observed in young, female, non-smoking patients with adenocarcinoma, consistent with the characteristics of this patient." (PMID 41487577, 2025). "Approximately 2–7% of patients with NSCLC demonstrate ALK rearrangements, predominantly in those with adenocarcinoma histology and who are light or never smokers." (PMID 41153394, 2025). "HP: poorly differentiated adenocarcinoma, ALK, EGFR negative, cT3N3M1b (OSS, single, right humeral head), stage IVA." (PMID 40429388, 2025).
adenocarcinoma (continued). "While anti-ALK IHC is primarily positive in adenocarcinoma within NSCLC, wild-type ALK without rearrangements is occasionally detected in other histological types, such as SCC." (PMID 38738001, 2024). "The adenocarcinoma showed epidermal growth factor receptor (EGFR) mutation, no anaplastic lymphoma kinase (ALK) expression, and less than 1% expression of programmed death ligand 1 (PD-L1) by immunohistochemistry." (PMID 38336778, 2024). "A multidisciplinary analysis was carried out; the typical clinical-radiographic presentation of adenocarcinoma was ruled out with immunohistochemistry, thus determining a diagnosis of ALK-negative anaplastic large cell non-Hodgkin's lymphoma." (PMID 38425329, 2024). "Most patients were in Stage IV (78.3%), had adenocarcinoma (89.1%) and were EGFR mutation-negative (76.1%) and ALK fusion-negative (89.1%)." (PMID 38594880, 2024). "ALK fusion is clinically more common in young adenocarcinoma patients who do not smoke or smoke infrequently, and the most common type of fusion is EML4-ALK." (PMID 36909198, 2023). "All cases harboring a BRAF V600 mutation were adenocarcinoma without EGFR mutation and ALK translocation." (PMID 37374289, 2023). "The ALK-testing methods included IHC (30/64, 46.9%), FISH (24/64, 37.5%), PCR (9/64, 14.0%), and NGS (1/64, 1.6%); the mean age of patients was 51.3 years (range 31–70); and 96.9% (62 of 64) of patients were with adenocarcinoma." (PMID 36424628, 2022). "In subgroup analysis, the median OS in patients with adenocarcinoma with EGFR/ALK wild type has not yet been reached." (PMID 35372004, 2022). "A higher survival benefit was observed in no PD‐L1 expression than with PD‐L1 expression in adenocarcinoma, EGFR and ALK mutation patients." (PMID 34841687, 2022). "All patients were untreated before enrollment and had histologically confirmed adenocarcinoma without sensitizing EGFR/ALK/ROS1 alterations." (PMID 34724131, 2022). "It is also conceivable that DARPP-32 might contribute to TKI therapy-refractory growth in adenocarcinomas in which additional downstream genetic alterations exist in genes like RET, ALK, BRAF, or KRAS, although such studies are yet to be conducted." (PMID 34675407, 2022). "A higher survival benefit (TTF or OS) was observed in no PD‐L1 expression than with PD‐L1 expression in adenocarcinoma, EGFR mutation, and ALK mutation patients." (PMID 34841687, 2022). "Moreover, patients with adenocarcinomas with positive epidermal growth factor receptor (EGFR) and anaplastic lymphoma kinase (ALK) alterations show improved survival compared to those without these alterations." (PMID 35455016, 2022). "In 2022, reflex testing for an ALK rearrangement in all newly diagnosed advanced NSCLC adenocarcinomas, not otherwise specified histology, or non-smoking squamous cancers, is the gold standard." (PMID 36003760, 2022). "Case #1 had an EGFR L858R mutant adenocarcinoma that was initially negative for ALK expression by immunohistochemistry (IHC)." (PMID 36153311, 2022). "Among 29 patients enrolled from May 2019 through August 2020, 21 (72.4%) had adenocarcinoma, 17 (58.6%) had a performance status of 2, 8 (27.6%) had asymptomatic brain metastases, and 13 (44.8%) had EGFR/ALK variations." (PMID 35372004, 2022). "Patients with ALK rearrangements are younger than those without ALK rearrangements, and most patients have little or no exposure to tobacco and present predominantly adenocarcinomas." (PMID 34063424, 2021). "A relatively high prevalence of ALK-positive cases (13%) was found in a selected population of Asian females with never/light smoking history and adenocarcinoma histology." (PMID 33435440, 2021). "According to the literature, 10–13% of Caucasian patients with adenocarcinoma (which represents the most part of non-squamous NSCLC) presents an EGFR activating mutation, 2–7% rearrangements of ALK and 1–4% BRAF mutations." (PMID 34885238, 2021).
adenocarcinoma (continued). "ALK+ NSCLC has been associated with the absence of smoking, younger age, and adenocarcinoma histology." (PMID 34660278, 2021). "In total, 52 patients were included [median age 57 years (range 32–81), 54% female, 62% never smokers, 98% adenocarcinoma]; 71% and 29% were ALK- and ROS1-positive, respectively." (PMID 33613692, 2021). "For example, ALK rearrangements are more common in non-smokers with adenocarcinoma than in smokers with adenocarcinoma or squamous cell carcinoma." (PMID 32104210, 2020). "Of the adenocarcinoma patients tested, 6/6 were negative for EGFR (epidermal growth factor receptor) mutation, 2/3 were ALK (Anaplastic lymphoma kinase gene) positive, and 1/5 were KRAS (Kristen rat sarcoma viral oncogene) mutant." (PMID 32754271, 2020). "Rearrangements of the anaplastic lymphoma kinase (ALK) gene are present in 3% to 5% of NSCLC and typically occur in younger patients who have never smoked or have a history of light smoking and that have adenocarcinoma histotype." (PMID 32397295, 2020). "Our data showed that ALK, ROS1, BRAF or KRAS gene alterations were significantly more frequent in adenocarcinomas with a mucus‐producing component or micropapillary component, and these two components could be a nonpredominant component in some cases." (PMID 32729257, 2020). "Fusions involving the rearranged during transfection proto-oncogene (RET) occur in 1–2% of NSCLC, and are more commonly seen in patients with minimal to no smoking history and adenocarcinoma histologic subtype, reminiscent of ALK and ROS1 fusions." (PMID 32183422, 2020). "The most frequent histological type was adenocarcinoma (76%) and Epidermal Growth Factor Receptor (EGFR) activating mutations were found in 9% of patients while no Anaplastic Lymphoma Kinase (ALK) translocations were detected." (PMID 32983959, 2020). "For ALK and ROS1-rearrangement positive adenocarcinoma patients might experience more benefit to pemetrexed-based chemotherapy, molecular characteristics would have been desirable." (PMID 31088547, 2019). "Of 785 adenocarcinomas, all the patients had their EGFR and ALK status identified." (PMID 31561631, 2019). "Among the unselected adenocarcinoma patients, EGFR and ERBB2 mutations and ALK fusions were frequent in nonsmoking female patients." (PMID 31387567, 2019). "Among the eight young and seven older adenocarcinoma patients with available data about ALK translocations, two patients (25%) and no one were identified as ALK translocation carriers, respectively." (PMID 30821106, 2019). "The characteristics of ALK-rearranged patients with c-Met overexpression were relatively young with less than 45 years old, and most of them were female and non-smokers with adenocarcinoma." (PMID 30477470, 2018). "ALK rearrangement is more commonly found in younger patients with adenocarcinoma histology who are light smokers or who have never smoked, and they are almost always mutually exclusive with other oncogenic drivers such as EGFR mutations." (PMID 29914100, 2018). "In our investigated cohort of triple-negative NSCLCs (EGFR, KRAS, and BRAF mutation negative) the number of cases with either ROS1 or RET fusions were similar to that of ALK-positive cases, supporting the need of multiplexed gene fusion diagnostics in NSCLC and adenocarcinoma specifically." (PMID 28415793, 2017). "ALK-negative patients had a mean age of 60 years (range 47 to 73 years), and were more likely to be male, never smokers, and have an adenocarcinoma histological type." (PMID 27926526, 2017). "An ALK rearrangement is detected in 3 to 7% of patients with stage IIIB/IV NSCLC, depending on the series and also probably according to the selection of the patients for molecular testing; in most cases it concerns an adenocarcinoma." (PMID 28805682, 2017). "Among HER2-overexpressing adenocarcinomas, 1 (16.7%) and 2 (33.3%) had EGFR and KRAS mutations, respectively, while none had ALK or ROS1 rearrangements." (PMID 28146588, 2017).
adenocarcinoma (continued). "Consistent with previously reported results, our study indicated that patients who were ALK-positive were predominantly young, never smokers, and had an adenocarcinoma histology." (PMID 27926526, 2017). "In order to adjust for confounding effect of pathological types, we made extra analyses of comparison of the metastatic sites between ALK‐positive patients and double‐negative ones only in adenocarcinoma patients." (PMID 28374971, 2017). "In our study, ALK‐positive patients were younger at diagnosis, and more of them were never smokers and with adenocarcinoma compared with both ALK‐ and EGFR‐negative patients." (PMID 28374971, 2017). "ALK rearrangements were frequent in younger patients, those who never smoked, adenocarcinomas, poorly differentiated tumors, signet ring cell types, and tumors with cribriform or solid patterns, also consistent with previous reports." (PMID 26992209, 2016). "This ALK gene rearrangement has been identified in 3-13 % of NSCLC patients and is significantly associated with young, female, non-smoking patients and with adenocarcinoma subtype with solid signet ring cell features and advanced stage of disease." (PMID 27142166, 2016). "In those studies, it was stated that ALK rearrangements were more common in nonsmoking patients, younger patients and adenocarcinoma histology and that it rarely coincided with the presence of an EGFR mutation." (PMID 27217997, 2016). "The ALK rearrangements that are found in up to 5 % of patients with NSCLC are related to younger age, no history of smoking and distinct clinicopathological features such as adenocarcinoma histology." (PMID 27217997, 2016). "One other study from Finland evaluated 87 NSCLC patients enriched for non-smokers and adenocarcinomas, and displayed an ALK fusion frequency of 5.7 %, which would also be considered as comparably low for selected patients." (PMID 27495736, 2016). "In this patient, NGS testing revealed ALK-rearranged adenocarcinoma, which had not been previously detected by FISH." (PMID 27480287, 2016). "Patients with ROS1 fusions shared some features in common with ALK-positive patients in previous studies, such as younger age, female sex, never-smoking status, adenocarcinoma, advanced stage and Asian ethnicity." (PMID 27563816, 2016). "VAMP2-NRG1 was reported in a 67-year-old never-smoker woman with adenocarcinoma with no mutation in EGFR, KRAS and BRAF and with no fusion genes involving ALK, ROS1 or RET." (PMID 27626312, 2016). "The frequency of ALK rearrangements was 20.3% (25/123) in young patients with the adenocarcinoma subtype who were non-smokers, which was also consistent with the previously reported results." (PMID 26253541, 2015). "ROS1 gene rearrangement and activation are detected in approximately 1–1.5% of NSCLC, predominantly in adenocarcinoma and in non-smokers, as is observed with ALK rearrangement." (PMID 26134262, 2015). "In 123 patients with adenocarcinoma who were non-smokers and of a young age (≤58 years old), the frequency of ALK rearrangement was 20.3% (25/123)." (PMID 26253541, 2015). "In conclusion, the patients who harbor ALK rearrangements tend to be relatively young, non-smokers or light smokers with the adenocarcinoma subtype." (PMID 26253541, 2015). "ALK-rearranged NSCLC tends to occur in younger individuals who are either non-smokers or light smokers with adenocarcinoma." (PMID 26253541, 2015). "ALK rearrangements are more frequently observed in younger patients, light or never-smokers, adenocarcinoma histology with frequent signet ring cells." (PMID 26208325, 2015). "A few ALK-rearranged tumors coexpressed p63 and TTF1 in the adenocarcinoma component." (PMID 26575266, 2015). "Patients had been diagnosed with either postoperative recurrence or metastatic NSCLC which were all adenocarcinoma, and all patients had ALK fusion gene-positive NSCLC without epidermal growth factor receptor mutations." (PMID 26819719, 2015).